NRP1 (neuropilin 1)
Diseases named in the same sentence as NRP1 in open-access papers (continued):
Sharing a sentence is not in itself a finding about the gene and the disease.
COVID-19 (continued). "The co-expression of ACE2, TMPRSS2, and NRP1 in the proximal tubules of normal kidney tissue should assist the infection of the virus and it could represent a mechanism for the direct kidney damage reported in patients affected by COVID-19." (PMID 38255667, 2023). "However, the structural difference of NRP1 between different species indicated that chickens NRP1 might exhibit low affinity to S CendR, which is different from that of species that are sensitive to coronavirus disease-2019 (COVID-19)." (PMID 37644471, 2023). "Thus, CD may be a therapeutic component for anti-cancer and anti-viral diseases, including COVID-19, by targeting NRP1 at least." (PMID 38138098, 2023). "However, these patients might be potential responders to the combination therapy of ICIs, chemokine inhibitors, and NRP1 inhibitors, which could be beneficial to suppressing tumor development, and controlling symptoms of COVID-19 at the same time." (PMID 36338984, 2022). "Although current evidence in support is scarce, it may be hypothesized that such a mechanism could also occur with respect to NRP-1 and perhaps contribute to the development of neurological and cardiovascular symptoms of long COVID-19 or some side effects of COVID-19 vaccines." (PMID 36557705, 2022). "Thus, a high NRP-1 serum level in COVID-19 could be a compensatory mechanism to overcome oxidative stress injury and mitochondrial dysfunction." (PMID 36009579, 2022). "NRP1 could be a valuable informative marker in predicting susceptibility to SARS-CoV-2 and the severity of COVID-19 patients, and it had a great potential as a therapeutic target especially in cancer patients combined with COVID-19." (PMID 36338984, 2022). "It has been confirmed that miR-24 serum level could be reduced secondary to high NRP-1 in COVID-19." (PMID 36009579, 2022). "However, the present study revealed that high NRP-1 serum in patients with COVID-19 and AIS depending on the previous findings might be a compensatory mechanism to overcome exaggerated immunity and neuroinflammation." (PMID 36009579, 2022). "Given the abundant expression of NRP-1 in the endothelium as well as in the nervous system, olfactory epithelium, and respiratory system, this alternative mechanism could explain the COVID-19 endotheliitis and other complications such as anosmia, dizziness, and headache." (PMID 36557705, 2022). "Therefore, NRP-1 may serve as a superfluous SARS-CoV-2 infection mediator involved in the neurologic manifestations of COVID-19." (PMID 36009579, 2022). "Neuropilin-1 could also be involved in the relationship between COVID-19 and diabetes mellitus." (PMID 33540664, 2021). "Elucidating this component would establish whether or not NRP1 partially drives the gender disparity associated with COVID-19 severity." (PMID 34025658, 2021). "In addition, the relationship of NRP1 and ACE2 expression to patients’ survivability rate followed by the coexpression analysis of genes positively regulated with these factors and associated with COVID-19 were studied." (PMID 34698182, 2021). "Usually, miR-24 is capable of repressing the expression of NRP1; however, a decrease in this miRNA has been shown in COVID-19, which could increase the expression of NRP1 and, along with this, increase the neurological damage caused by the virus entering neuronal cells." (PMID 35062245, 2021). "Therefore, along with the ACE2, a high expression of the newly identified host factor NRP1 in renal carcinomas may play a vital role in the increased risk of SARS-CoV-2 infection and high mortality of COVID-19 patients suffering from kidney cancers." (PMID 34698182, 2021). "Despite organ-specific studies on ACE2 and other SARS-CoV-2 co-factors, detailed characterization of NRP1 and NRP2 expression in COVID-19-infected tissues remains limited." (PMID 41159753, 2025).
COVID-19 (continued). "To complement these findings, we analyzed NRP1 and ACE2 transcript levels in lung samples from healthy individuals and COVID-19 patients using data from GEO (GSE150316)." (PMID 40722799, 2025). "This study aims to provide a comprehensive assessment of NRP1 and NRP2 protein expression in the heart, lung, and hematolymphoid organs of COVID-19 autopsies using immunohistochemistry (IHC)." (PMID 41159753, 2025). "This study presents a detailed in situ analysis of Neuropilin 1 (NRP1) and Neuropilin 2 (NRP2) expression in fatal COVID-19 cases using immunohistochemistry and spatial multiplex immunofluorescence phenotyping, complemented by single cell RNA sequencing." (PMID 41159753, 2025). "Decreased phagocytosis in severe COVID-19 was evident by the downregulation of MSR1, Neuropilin 1 (NRP1), and MRC1, with more significant decreases in SevereD." (PMID 39928675, 2025). "This study presents a comprehensive analysis of NRP1 and NRP2 protein expression in COVID-19 in situ by IHC and CODEX, alongside transcriptomic data from publicly available scRNAseq data sets." (PMID 41159753, 2025). "Since NRP1 plays a role in endothelial cell adhesion and permeability and has a coagulation binding domain, it may contribute to inflammation and the pathophysiology of COVID-19 by releasing intracellular factors after endothelial injury induced by SARS-CoV-2 infection." (PMID 40431631, 2025). "It is possible that not only the cell tropism based on NRP1 and NRP2 expression contributes to the pathology of acute COVID-19 and PASC, but also the differential binding of neuropilins to proteolytic spike fragments." (PMID 41159753, 2025). "The S protein has a higher affinity for binding to NRP-1 than VEGF-A because the binding of S1 to NRP-1 cells destabilizes the NRP-1/VEGFR-2 complex, which displaces VEGF-A, contributing to the high serum concentrations of VEGF-A in patients with COVID-19." (PMID 40008234, 2024). "Recently, NRP-1 has been identified as a facilitator of cell entry and infectivity in SARS-CoV-2 infection and COVID-19." (PMID 38791476, 2024). "ACE2-positive brain cells from COVID-19 patients showed that expression of major genes involved in endothelial dysfunction was also significantly higher than in control cells, with BSG and NRP1 highly expressed in ACE2-positive cells infected with SARS-CoV-2." (PMID 37239234, 2023). "Both NRP1 and NRP2 were extracted in high concentrations from the lung tissue of deceased COVID-19 patients." (PMID 35021853, 2022). "As COVID-19 is mainly characterized by severe symptoms in the respiratory system, we wanted to find out the expression profile of the SARS-CoV-2 receptor NRP1 among NSCLC patients." (PMID 36338984, 2022). "In contrast, in macrophage/monocyte and dendritic cells, the proportion co-expressing NRP1 with CTSL and FURIN was reduced in COVID-19 patients’ lungs." (PMID 35458567, 2022). "In conclusion, a natural peptide, tuftsin, shows high potency of treating COVID-19 along with the immunomodulation effect, and exhibits satisfactory ACE2 and NRP1-targeting ability." (PMID 35402510, 2022). "Moreover, the low nasal congestion (3.7%) and the rare rhinorrhea in COVID-19 cohorts supports the idea that there is neurological dysfunction in the olfactory bulbs, suggesting that NRP1 could be a possible candidate for the physiopathology mechanism of the anosmia in COVID-19." (PMID 35053224, 2022). "In the COVID-19 pathway, the SARS-CoV-2 receptors ACE2 and NRP1, some immune molecules such as IL-2, STAT1, and some complement molecules are the targets of tuftsin." (PMID 35402510, 2022). "NRP-1 mRNA expression level had a significant positive (p = 0.000) correlation with both TLR2 and TLR4 mRNA expressions in moderate COVID-19 patients." (PMID 35891270, 2022). "The net effect of NRP-1 in COVID-19 with AIS is through the induction of anti-inflammatory and antioxidant effects which reduce the severity of both COVID-19 with AIS." (PMID 36009579, 2022).
COVID-19 (continued). "Two pathways were determined, namely SARS-CoV-2 and COVID-19 pathway (WP4846) and SARS-CoV-2 altering angiogenesis via NRP1 (WP5065)." (PMID 36338984, 2022). "Collectively, these data suggest the involvement of NRP-1 in SARS-CoV-2 cell infectivity and define an additional potential target for antiviral intervention in pulmonary and neurological manifestations of COVID-19." (PMID 35002503, 2022). "Therefore, NRP-1/FoxP3 is an important axis that regulates Treg cells’ function, prevents exaggerated immune response in COVID-19, and could be a possible prognostic factor for patients with severe COVID-19." (PMID 36009579, 2022). "In this context, autoantibodies such as ACE2-aab, AGTR2-aab, BDKRB1-aab, CXCR3-aab, MAS1-aab, CHRM5-aab, NRP1-aab, F2R-aab, STAB1-aab appeared to play a major role in stratifying COVID-19 by disease burden." (PMID 35264564, 2022). "Recently, NRP1 has been discovered as a coreceptor for the SARS-CoV-2 viral entry, along with ACE2, and has thus become one of the COVID-19 research foci." (PMID 35955539, 2022). "However, it has not been investigated whether the dysfunction of the NRP-1/VEGF-A system caused by the SARS-CoV-2 S protein may be directly associated with adverse events in COVID-19 vaccine recipients." (PMID 36557705, 2022). "Therefore, high NRP-1 in COVID-19 might be due to over-expressed HIF-α1." (PMID 36009579, 2022). "Our analysis suggests NRP1 as a potential therapeutic target, while sets an alert on targeting TMPRSS2 for treating comorbidity of COVID-19 and lung cancers." (PMID 34168096, 2021). "NRP1 is a transmembrane glycoprotein, which is expressed in endothelial cells, and serves as a receptor for vascular endothelial growth factor (VEGF), and both NRP1 and VEGF expression are increased in COVID-19 patients." (PMID 33521617, 2021). "TMPRSS2 and Neuropilin-1, the key components that facilitate SARS-CoV-2 infection, are potential targets for treatment of COVID-19." (PMID 34168096, 2021). "The SARS-CoV-2 virus can enter a host cell by the interaction of the COVID-19 spike glycoprotein and the ACE2 receptor or another receptor, neuropilin-1 (NRP1), of the host cell." (PMID 33921174, 2021). "Moreover, NRP-1 may also serve as an immune checkpoint of the memory T cell in COVID-19." (PMID 34209289, 2021). "Due to the roles in SARS-CoV-2 infection, ACE2, NRP1 and TMPRSS2 are targets for drug design for COVID-19." (PMID 34168096, 2021). "Here we performed a comprehensive analysis on NRP1 and TMPRSS2 in lung to provide information for treating comorbidity of COVID-19 with lung cancer." (PMID 34168096, 2021). "ACE2 expression level is hardly detective in peripheral blood or lung compared with NRP1 and TMPRSS2, and ACE2 downregulation after viral infection increases the severity of COVID-19 disease." (PMID 34168096, 2021). "In autopsies of patients who succumbed to COVID-19, SARS-CoV-2 was found in NRP-1-positive olfactory cells in nasal passages, the olfactory bulb, and olfactory tracts in the brain." (PMID 33395426, 2021). "Therefore, it might be suggested that, along with the ACE2, high expression of the newly identified host factor NRP1 in renal carcinomas may play a vital role in the increased risk of SARS-CoV-2 infection and survivability of COVID-19 patients suffering from kidney cancers." (PMID 34698182, 2021). "Also in the lung, intussusceptive angiogenesis in COVID-19 has been demonstrated, accompanied by an upregulation of NRP1, NRP2, and VEGFA, in partial agreement with our own findings of NRP1 and NRP2 protein and transcript expression in the lung." (PMID 41159753, 2025). "Additionally, renal and cardiac dysfunctions have been linked to the cytokine storm in patients with severe and moderate COVID-19, correlating with increased ACE2 and NRP1 expression." (PMID 40431631, 2025).
COVID-19 (continued). "We detected a significant upregulation of NRP1 transcripts in vascular ECs in COVID-19 lungs compared with noninfectious controls (P < 7.5E-6), while ACE2 and TMPRSS2 expression remained unchanged." (PMID 41159753, 2025). "By mapping ambroxol’s potential target to Coronavirus disease—COVID-19 pathway in KEGG, we found that ambroxol might interact with the SARS-CoV-2 cell entry receptor, NRP-1, on cellular surface." (PMID 36651548, 2023). "NRP1 has another isoform, NRP2, whose function in COVID-19 has seldom been reported." (PMID 37515185, 2023). "Simultaneously targeting Mpro/NRP1 by one entity is a promising and novel COVID-19 therapeutic that nearly no reported." (PMID 36408220, 2022). "On the other hand, the expression of olfactory NRP-1 and other receptors for SARS-CoV-2 entry is low in newborns, which might explain mild neurological and other COVID-19 symptoms in newborns." (PMID 36009579, 2022). "Moreover, semaP3A/NRP-1 pathway is required for TLR4 activation, which plays an integral role in the development of immunological disturbances during COVID-19 and AIS." (PMID 36009579, 2022). "Our study demonstrated a significant positive correlation between NRP-1 expression and cardiac damage biomarkers (rise of serum LDH and CK-MB activities and troponin I level) in both moderate and severe COVID-19 groups; the correlation was augmented by severity of infection." (PMID 35891209, 2022). "NRP-1 has the potential capability to attenuate neuroinflammation, blood–brain barrier (BBB) permeability, cerebral endothelial dysfunction (ED), and neuronal dysfunction that are uncommon in COVID-19 with neurological involvement, including AIS." (PMID 36009579, 2022). "Disease transmission in asymptomatic subjects may be affected by manipulating the VEGF-A165a subtype/b1 domain of neuropilin-1 (NRP-1) signaling, which is upregulated at the transcriptional level in COVID-19." (PMID 36140343, 2022). "Thus, the semaP3A/NRP-1 pathway is involved in the progression of harmful consequences in both AIS and COVID-19." (PMID 36009579, 2022). "COVID-19′s epidemiological and clinical characteristics and its effects on the levels of both types of cytokines (pro- and anti-inflammatory), kidney and heart function biomarkers, and ACE-2 and NRP-1 expression levels are presented in this study." (PMID 35891209, 2022). "In conclusion, NRP-1 has an important role in the pathogenesis of COVID-19 and AIS, and could be the potential biomarker linking the development of AIS in COVID-19." (PMID 36009579, 2022). "In eleven COVID-19 patients, we examined the expression of ACE2, TMPRSS and other receptors and factors, such as DPP4, HMBG1 and NRP1, that might facilitate virus entry." (PMID 34112801, 2021). "In addition, coexpression analysis of genes involved in COVID-19, KIRC, and KIRP concerning NRP1 and ACE2 was performed." (PMID 34698182, 2021). "NRP1 serves as a host factor for SARS-CoV-2 infection and may potentially provide a therapeutic target for COVID-19." (PMID 33082293, 2020). "The molecular mechanisms triggered by the binding of the S protein to its cellular receptors, such as ACE2, TLR2/4, NRP1, DPP4, and CD147, among others, across various tissues and organs, provide valuable insights and are essential in understanding the pathophysiology of both COVID-19 and LC." (PMID 40431631, 2025). "However, contrary to previous results, we did not detect relevant NRP1 mRNA in Tregs in COVID-19 lungs." (PMID 41159753, 2025). "Blocking of NRP1/S-protein interaction with small-molecule inhibitors or monoclonal antibodies (mAbs) may reduce SARS-CoV-2 infectivity and provide potential intervention strategies for COVID-19 management." (PMID 38555403, 2024). "Thus, NRP2 affects SARS-CoV-2 proliferation in coordination with NRP1 and ACE2 under inflammatory conditions and may serve as a novel therapeutic target for COVID-19 treatment." (PMID 37515185, 2023).
COVID-19 (continued). "Since olfactory epithelial cells in COVID-19 patients have high levels of NRP-1 and VEGF-A is a ligand for NRP-1, this implies that one explanation for the patient's cognitive and neurological impairments could be the sensitivity of these brain regions to SARS-CoV-2." (PMID 37189112, 2023). "In addition, cells from the bronchioalveolar lavage of COVID-19 patients showed an increase in NRP1 RNA expressions in SARS-CoV-2 positive cells but not in uninfected cells, further enhancing SARS-CoV-2 entry." (PMID 38138098, 2023). "Moreover, proinflammatory cytokines synthesized during COVID-19 or in response to vaccines may promote the expression of VEGF-A, whereas inflammation and hypoxia may decrease the expression of VEGF-R2, NRP-1, and NRP-2, as observed in preclinical studies." (PMID 36557705, 2022). "In our previous publication, the correlations between cytokine levels, liver function markers, and neuropilin-1 expression in patients with COVID-19 were assessed, but the relation between cytokine levels and pulmonary dysfunction and lung injury in those COVID-19 patients were not evaluated." (PMID 36675695, 2022). "Moreover, the semaP3A/NRP-1 pathway is required for the activation of toll-like receptor 4 (TLR4), which plays an integral role in the development of immunological disturbances during COVID-19." (PMID 36009579, 2022). "We hope our research could emphasize NRP1 as a reliable biomarker in predicting vulnerability to SARS-CoV-2 infection in cancer patients and provide potential strategy to treat cancer patients combined with COVID-19." (PMID 36338984, 2022). "Therefore, NRP1 was shown to act as a host factor for SARS-CoV-2 infection and could potentially provide a selective therapeutic target to counter COVID-19." (PMID 35327455, 2022). "Finally, the expression level of NRP1 and TMPRSS2 in COVID-19 patients was analyzed using the public datasets: NRP1 is decreased in peripheral blood of COVID-19 patients admitted to intensive care unit (ICU), but the level of NRP1 in the lung of COVID-19 patients is not changed." (PMID 34168096, 2021). "Therefore, successful blockade of the interaction between SARS-CoV-2 and NRP-1 by using well established inhibitors, such as EG00229 and EG01377, may prove to be an effective COVID-19 therapy." (PMID 34572076, 2021). "We thus performed NRP-1 immunohistochemical staining of lung tissue from our autopsied cohort with an antibody directed against NRP-1 and demonstrated that NRP-1 expression (positive staining as % of area) was drastically increased in patients who died of COVID-19." (PMID 34745111, 2021). "Thus, it is plausible to speculate that mdig dependent expression of NRP1 and NRP2 can enhance the infectivity of SARS-CoV-2, leading to the worsening effect of environmental exposure on the severity of COVID-19." (PMID 34335974, 2021). "However, NRP1 and DPP4 may have opposing roles in COVID-19 pathogenesis." (PMID 40431631, 2025). "Finally, analysis of scRNA-seq data showed that NRP1 RNA expression levels were elevated in SARS-CoV-2 positive bronchial epithelial cells compared with SARS-CoV-2 negative cells and adjacent bronchoalveolar lavage fluid (BALF) cells from severely affected COVID-19 patients." (PMID 37047226, 2023). "In the latest in silico study molecular compounds previously investigated in COVID-19 related studies were screened against NRP1 to obtain that Nafamostat, Y96, Selinexor, Ebastine and UGS may emerge as good candidates for preventing the binding of spike to NRP1." (PMID 35955539, 2022). "Moreover, NRP1 is not decreased in the lung tissue of COVID-19 patients." (PMID 34168096, 2021). "NRP1 and NRP2 proteins were heterogeneously expressed in larger vessel EC of the trachea and lung of COVID-19 patients, while absent from small capillaries." (PMID 41159753, 2025).